BRAF (B-Raf proto-oncogene, serine/threonine kinase)
Diseases named in the same sentence as BRAF in open-access papers (continued):
Sharing a sentence is not in itself a finding about the gene and the disease.
tumor (continued). "In the United States, the FDA approved ivosidenib for IDH1 mutations and pemigatinib, infigratinib, and futibatinib for FGFR2 fusions, alongside tumor-agnostic treatments for mismatch repair deficiency, NTRK fusions, ERBB2 amplifications, BRAF V600E mutations, and RET fusions." (PMID 39996880, 2025). "Similar to our findings, studies have shown that Mortalin can regulate mitochondrial membrane permeability and membrane potential by inhibiting the interaction between SLC25A6 and CypD, which suppresses mPTP opening, ultimately promoting the survival of BRAF-mutant tumor cells." (PMID 40841355, 2025). "An important question is whether MAP2K1-driven tumours align with conventional WHO melanomagenesis pathways, alongside BRAF, NRAS, and NF1 mutations, or pathway IV (Spitz), alongside kinase gene fusions and HRAS mutations." (PMID 40107205, 2025). "Por este motivo se han ensayado otras combinaciones de drogas, por ejemplo en un ensayo clínico de fase 2 se realizó una inhibición combinada de PD-1 (espartalizumab), BRAF (dabrafenib) y MEK (trametinib) fortaleciendo así la respuesta inmune que suele estar alterada en muchos tumores." (PMID 40977817, 2025). "SLC5A8 was postulated as a potent tumor suppressor and its lowered levels were shown in numerous malignancies, including follicular thyroid carcinoma and papillary thyroid carcinoma, where its suppression seems to be BRAF-dependent and is related to tumor aggressiveness." (PMID 40869209, 2025). "Still, in node-negative colon cancer, a group with generally good prognosis, some develop disease recurrence; determining both tumor–stroma ratio (TSR) and BRAF (B-Raf proto-oncogene, serine/threonine kinase) mutations might help in prognostication." (PMID 41503067, 2025). "Notably, Ulixertinib reduced or blocked tumor growth in patients with resistance to prior BRAF/MEK-targeted inhibitors (e.g., Vemurafenib or Trametinib), as well as in those harboring non- BRAF mutations." (PMID 40723336, 2025). "For instance, Levistolide A could be paired with BRAF or PI3K inhibitors to enhance tumor suppression, while Senkyunone’s pro-apoptotic effects may reduce chemo or radiotherapy doses." (PMID 40128073, 2025). "We demonstrated the transition of PTC to SCC, in which tumor cells carried none of the common driver mutations (e.g. BRAF or RAS), but showed biallelic inactivation of KEAP1, STK11, and RB1." (PMID 40600748, 2025). "Oncogenic BRAF mutations lead to constitutive activation of the MAPK/ERK pathway, resulting in uncontrolled proliferation, survival, invasiveness, and drug resistance of tumor cells." (PMID 40492122, 2025). "Moreover, we observed that the combination of 5-Fu with cetuximab and Remodelin increased tumor regression in our xenograft mouse model of wild-type KRAS/NRAS/BRAF CRC." (PMID 39905540, 2025). "Moreover, in cetuximab-resistant PDX models and mouse models harboring KRAS or BRAF mutations, HTI-1511 significantly inhibited and even reversed tumor growth." (PMID 40469310, 2025). "Immunohistochemistry often reveals positive BRAF V600E expression in the cytoplasm of tumor cells." (PMID 40696244, 2025). "Certain oncogenic mutations in BRAF cause the BRAF proteins to become activated on their own, permanently activating MEK1/2 and ERK1/2 via the MAPK pathway and promoting the formation of tumours." (PMID 40831998, 2025). "Univariate analyses also revealed a significantly higher likelihood of tumor relapse or tumor-related death among patients with PTCs whose cells showed TERT amplification concurring with other genetic alterations such as TPM, BRAF, or TPM + BRAF mutations." (PMID 40272676, 2025). "However, G-5555 partially re-sensitized Rac1-driven BRAFi-resistant tumor cells to BRAF inhibition, both for Vav1 over-expressing cells and for cells expressing the clinically relevant Rac1 P29S constitutively active mutant." (PMID 41109929, 2025).
tumor (continued). "This technique identifies the co-occurrence of tumor subpopulations with and without the BRAF V600E mutation." (PMID 40977811, 2025). "In the lymph nodes, BRAF V600E IHC can highlight metastatic isolated tumor cells or clusters, which could be missed on routine H&E evaluation." (PMID 40111709, 2025). "The tumor was screened for BRAF fusion (Oncomine FOCUS panel, ThermoFisher Scientific), and mutations in the BRAF or IDH1/2 genes (therascreen RGQ PCR, Qiagen), but no genetic alterations could be found." (PMID 39326005, 2025). "The wide variability in metastasectomy rates (13–43%) and survival (mOS 44–93 months) according to primary tumour location, MMR-status, and mutation status are most probably explained by the differences in RAS-, BRAF-, and MMR-status which, thus, seem most important." (PMID 40437037, 2025). "This negative prognostic effect was confirmed after multivariate analysis and matching for all those stratification factors that are usually considered to have an impact on both PFS and OS (tumor sidedness, RAS and BRAF mutational status, ECOG-PS at treatment start)." (PMID 39591103, 2025). "The development of strategies to reshape the tumor microenvironment, such as combining BRAF inhibitors with antifibrotic agents or immune modulators, may enhance treatment efficacy and overcome drug resistance." (PMID 41255582, 2025). "Patients with BRAF or KIT mutations may benefit from BRAF inhibitors, which selectively inhibit mutated signaling pathways, thereby slowing tumor progression and improving clinical outcomes." (PMID 40395262, 2025). "In the post-treatment tumor specimen of Patient 1, there was emergence of BRAF copy number amplification, which is a known mechanism of resistance to type 1 RAF inhibition in cancer cells harboring the BRAF p.V600E mutation." (PMID 40634537, 2025). "Evidence suggests that inhibition of a single RTK may be insufficient to overcome primary resistance to MAPK-pathway inhibition in BRAF-mutant tumours." (PMID 40332222, 2025). "Patients without available NGS due to low tumor cellularity and/or limited tissue availability and without BRAF mutations identified via IHC/PCR were considered to have incomplete genetic assessment and not included in our study." (PMID 39934281, 2025). "PTEN is a tumor suppressor gene that regulates the PI3K/AKT pathway, affecting cell growth and survival, and loss of PTEN function promotes further aggressiveness of the BRAF V600E mutation." (PMID 40344620, 2025). "Additionally, genetic alterations such as BRAF:p.V600E, RAS mutations, TERT promoter mutations, and RET/PTC rearrangements provide molecular insights into tumor progression and therapeutic response." (PMID 40940966, 2025). "A promising strategy involves combining BRAF inhibition with immune checkpoint inhibitors, which could enhance tumor antigenicity and boost immune response." (PMID 41255582, 2025). "Preclinical studies have demonstrated that silencing of MALAT1, HOTAIR, or SAMMSON using antisense oligonucleotides (ASOs) or gapmeRs dramatically reduces intratumoral vessel density and tumour growth and shows synergistic effects with BRAF/MEK inhibitors and bevacizumab." (PMID 41463281, 2025). "The Ki67 index was 7%, and the tumor harbored an EVI5::BRAF genetic fusion." (PMID 39940949, 2025). "Furthermore, we demonstrated in both BRAFV600E CRC cell line xenograft mouse models and PDXs that dual inhibition of SRC and BRAF synergistically reduced tumor growth compared with single-drug therapy." (PMID 40481178, 2025).
tumor (continued). "This low likelihood, together with the fact that the majority of patients with BRAF V600E-mutant mCRC require an intensive first-line regimen to control the aggressive tumor growth, supports the investigation of EC+mFOLFOX6, and led to the early closure of EC arm enrollment." (PMID 39863775, 2025). "In addition to BRAF p.V600E status, tumor characteristics such as tall cell subtype, tumor size, and volume of nodal involvement are also considered when determining treatment." (PMID 40237893, 2025). "It is notable that both of the two patients who had progressed on BRAF inhibitors responded to luvometinib, indicating that luvometinib may be able to overcome tumour resistance to BRAF blockade." (PMID 41035796, 2025). "A dedicated study involving exclusively RAS/BRAF wild-type patients would be necessary to establish whether anti-EGFR therapy is superior to anti-VEGF therapy in terms of inducing tumor fibrosis ≥40%." (PMID 40507350, 2025). "Indeed, BRAF inhibition is able to alter the tumor-immune interactions, leading to the formation of significant barriers to reach therapeutic success." (PMID 40872623, 2025). "High tumor mutational burden (TMB) is associated with immunotherapy, and several genes related to high TMB, including ARID1A, RNF43, BRAF, and KM2B in microsatellite instability (MSI) tumors, may also be used for the treatment of MSS patients." (PMID 40242245, 2025). "Data on BRAF mutation, PD‐L1 expression, and tumor mutation burden were not included, as enrollment preceded routine testing for these features." (PMID 40536492, 2025). "However, when surgical resections are incomplete, often due to tumor location, treatment of BRAF/MAPK-signaling is an option." (PMID 39326005, 2025). "While KRAS, NRAS, and BRAF hot-spot mutations are very important drivers of tumorigenesis and tumor progression, it is important to note that they are not the only intrinsic features of colonic tissues dictating its consequences for tumorigenesis." (PMID 39857025, 2025). "For clarity, we define “regressing tumors” as those undergoing active shrinkage during the early phase of BRAF/MEKi treatment (e.g., day 3), while “residual disease” refers to the stabilized, therapy‐tolerant tumor state observed after prolonged treatment (e.g., day 14), prior to overt resistance." (PMID 40847444, 2025). "Additionally, the mutation profiles differ, with right-sided tumors more frequently showing BRAF mutations, while left-sided tumors show higher rates of APC and KRAS mutations.5) Moreover, responses to systemic therapy vary based on tumor location." (PMID 41139484, 2025). "Furthermore, the molecular characterization of the tumor as RAS/BRAF wild-type enabled the use of targeted therapies, improving the precision of the therapeutic approach." (PMID 40863225, 2025). "Only 35% underwent molecular testing, identifying BRAF mutations in 11% of those tested; no patients received circulating tumor DNA analysis." (PMID 41375623, 2025). "Indeed, tumor-related mutations (e.g., EGFR, BRAF, KRAS, PTEN, MET) have been found in up to 63% of patients with brain metastases but no apparent LMD." (PMID 39859576, 2025). "The positive BRAF result is considered conclusive, as none of the tumour-free dogs in the study cohort contained the BRAF mutation." (PMID 40872680, 2025). "Notably, the combination of VSIG4 blockade and BRAF inhibitor remarkably improved the anti-tumor activity, which provides a translational opportunity for ATC treatment." (PMID 39920772, 2025). "In contrast, the success of dabrafenib plus trametinib in BRAF-mutant ATC demonstrates that targeted therapy can achieve profound tumor regression, while emerging evidence suggests MAPK inhibition may also favorably remodel the TIME." (PMID 41562080, 2025).
tumor (continued). "Moreover, tumour histology was examined regarding RAS and BRAF mutation status, highlighting a significant difference between patient’s sex: RAS mutation was detected in 54% of analysed female samples and only in 34% in male ones (p = 0.005)." (PMID 39984882, 2025). "He began neoadjuvant BRAF/MEK inhibitor therapy to shrink the tumor and resolve metastasis." (PMID 41641291, 2025). "RNF43 and BRAF are molecular events involved in the serrated tumor pathway during CRC development." (PMID 40860811, 2025). "SECA-II required stable disease on first-line ST, absence of BRAF V600E mutations, ≤3 chemotherapy lines, and favorable tumor profiles, achieving a 5-year OS of 83%." (PMID 41002551, 2025). "When tumor cells are treated with BRAF inhibitors and MEK inhibitors, they may enhance autophagic flux to eliminate the damaged organelles and abnormal proteins induced by these agents." (PMID 40331942, 2025). "Three patients of all had received a prior systemic tumor therapy, one patient with irHypophysitis and one patient of the other irAE group had received BRAF/MEK‐inhibitor therapy before, and one patient of the control group with other irAE had received tyrosine kinase inhibitor therapy, previously." (PMID 39831665, 2025). "BRAF V600E mutations are significantly more common in microsatellite instability-high (MSI-H) tumors compared to microsatellite-stable (MSS) tumors, due to their involvement in the serrated neoplasia pathway." (PMID 40332392, 2025). "The aim of this study was to quantify the expression levels of the immune checkpoint molecules TIM-3 and Gal-9 in CRC tissues and adjacent non-tumor tissue, and to investigate their associations with key oncogenic mutations, including KRAS, NRAS, BRAF, PIK3CA, and AKT1, as well as MSI status." (PMID 40724985, 2025). "Moreover, the combination of VSIG4 blockade with a BRAF inhibitor synergistically enhanced anti-tumor activity in ATC-tumor bearing mice." (PMID 39920772, 2025). "This fundamental difference in tumor biology could influence the prognostic significance of RAS and BRAF mutations in each subtype." (PMID 39628993, 2024). "PF-07284892, an allosteric SHP2 inhibitor, combined with encorafenib and binimetinib, overcame bypass-signaling-mediated resistance in various tumor models, including BRAF V600E-mutant colorectal cancer, presenting a valuable model for testing novel drug combinations." (PMID 39684685, 2024). "Evaluate the relationship between VC intake and the survival of individuals with CRC, considering the presence or absence of KRAS or BRAF mutations in the tumor." (PMID 39130946, 2024). "Additionally, because both KRAS c.34G>T (p.G12C) mutation and BRAF mutation were associated with CIMP‐high status, we conducted exploratory analyses comparing clinical and tumor characteristics between KRAS c.34G>T (p.G12C)‐mutated and BRAF‐mutated tumors." (PMID 39039804, 2024). "The distribution of tumor size was different across types of mutations at diagnosis: tumors with BRAF mutations were smaller (p < 0.001) than tumors without mutation." (PMID 38337794, 2024). "CNMs count has a predictive role regardless of tumor size; their association with the BRAF V600E mutation suggests their predictive significance in response to biologics." (PMID 39099686, 2024). "Recent studies have shown that, in addition to directly targeting tumor cells, BRAF inhibitors may also enhance anti-tumor effects by modulating the immune response within the tumor microenvironment." (PMID 39529955, 2024).
tumor (continued). "In the BRAF mutant context, all but the weakest clinically realized combinations of Belvarafenib and Cobimetinib perform similarly, inhibiting tumor growth, as shown by the corresponding GR metric values, without significant synergistic effects, as shown by low Bliss excess values." (PMID 39199684, 2024). "Our case has enriched the spectrum of jaw bone tumor and BRAF rearrangement tumor." (PMID 38606111, 2024). "FDA recently approved a BRAF/MEK-inhibitor combination for BRAF mutated tumours, regardless of primary tumour site." (PMID 38909137, 2024). "Finally, the limited availability of tumour biomarkers (e.g. BRAF, NRAS) restricts our analysis and comprehensive understanding of the biological behaviour of the tumour in patients with mCRC." (PMID 39177674, 2024). "BRAF encodes a serine/threonine protein kinase of the RAF family and is involved in the regulation of the RAS-RAF-MEK-ERK signaling, which is activated in tumor growth and progression, including proliferation, angiogenesis, invasion, and metastasis." (PMID 39410512, 2024). "Furthermore, Clark invasion level and pT category had an independent significant effect on tumor response to BRAF + MEK inhibitor treatment." (PMID 39272837, 2024). "This envisions a synergistic use of ctDNA tracking and NGS analysis under the guidance of the BRAF-mutant ctDNA absolute amount, which appears more accurate in defining the tumor burden and more reliable in comparing different time points being unaffected by external influences." (PMID 38548846, 2024). "Since Dabrafenib is a clinically used agent for Ep‐GBM patients with the BRAF V600E mutation, we further investigated whether NU7441 treatment enhanced the anti‐tumor efficiency of Dabrafenib toward Ep‐GBM‐like tumors." (PMID 38828688, 2024). "Additionally, we didn’t have all the molecular tumor characteristics such as NRAS and BRAF mutations, which also affect the response to anti-EGFR antibody therapy." (PMID 39202071, 2024). "Additionally, we analyzed the patients’ therapy in conjunction with their tumor stage and BRAF status." (PMID 39125519, 2024). "Type II RAF inhibitors result in tumor response regardless of the BRAF alteration type (mutation or fusion) without a risk of paradoxical activation." (PMID 39399174, 2024). "Additionally, we investigated the therapy of patients, depending on the tumor stage and the BRAF result." (PMID 39125519, 2024). "For BRAF V600E-mutated tumors, combining encorafenib with anti-EGFR agents such as cetuximab has shown promise, as this approach disrupts multiple signaling pathways that contribute to tumor growth and chemotherapy resistance." (PMID 39684219, 2024). "These diagnostic assays are necessary not only to determine the histologic characteristics of the tumor but also to select a treatment regimen, taking into account the possibility of targeted therapy with BRAF inhibitors, checkpoint inhibitors (immunotherapy), etc.." (PMID 39518386, 2024). "Moreover, we verify that the relation between tumor metabolism and BRAF inhibition has the potential for significant clinical translational implications." (PMID 38254853, 2024). "RAS/BRAF testing on tissue using real-time PCR showed a wild-type tumor." (PMID 39064004, 2024). "However, while agents that target the WNT pathway remain in development, the availability of BRAF inhibitors such as vemurafenib and dabrafenib has proven effective in reducing the tumor size in patients with papillary craniopharyngiomas." (PMID 39061172, 2024). "Since only 34 of 52 (65%) patients had sufficient tumor DNA to be used for a BRAF/KRAS mutation analysis, there was no exact evidence to show that there was an association between the mutation status and treatment response." (PMID 38669365, 2024).